STAT3 (signal transducer and activator of transcription 3)
Diseases named in the same sentence as STAT3 in open-access papers (continued):
Sharing a sentence is not in itself a finding about the gene and the disease.
pancreatic cancer (continued). "Here, we show for the first time that liposomal delivery of FLLL32, a STAT3 phosphorylation inhibitor, efficiently suppressed pancreatic cancer xenograft tumor growth, and sensitized pancreatic cancer cells to radiotherapy in vitro and in vivo by inhibiting STAT3 signaling in CSCs potentially." (PMID 26887043, 2016). "In conclusion, we have demonstrated for the first time that OV could potentially inhibit Mia-PaCa2 pancreatic cancer cells proliferation and induce apoptosis through modulation of NF-κB and STAT3 pathway." (PMID 27242913, 2016). "In addition, a connection between gemcitabine and STAT3 is plausible as inhibition of STAT3 was observed to enhance the response to gemcitabine in a pancreatic cancer animal model." (PMID 27687804, 2016). "To investigate whether pSTAT3 is also involved in gemcitabine-enhanced migration and invasion in pancreatic cancer cells, we examined phosphorylated STAT3 (pSTAT3) and total STAT3 protein levels after gemcitabine treatment." (PMID 27556697, 2016). "Interestingly, TAM can directly enhance the tumor-initiating capacity of pancreatic cancer cells by activating the transcription factor STAT3, thereby facilitating macrophage-mediated suppression of CD8+ T lymphocytes." (PMID 27191744, 2016). "Furthermore, EGCG induces apoptosis and suppresses pancreatic cancer cell growth, metastasis by suppressing STAT3 transcription and activation." (PMID 27036017, 2016). "Furthermore, we evaluated the effects of RES and TRES on the modulation of the key molecular targets in STAT3 and NFкB, as well as their interaction and translocation into the nucleus of pancreatic cancer cells." (PMID 27539371, 2016). "The present study indicates that LTP-1, a novel synthetic arylsulfonamide derivative, acts by suppressing pancreatic cancer cell growth, inducing tubulin destabilization, and may exhibit a dual effect to inhibit Stat3 phosphorylation." (PMID 27278358, 2016). "Moreover, it was recently shown that STAT-3 overexpression or STAT-3 activation by IL-6 significantly increased the levels of β-catenin in pancreatic tumor cells, and this effect inhibited β-catenin signaling." (PMID 26418031, 2015). "In addition, signal transducer and activator of transcription 3 (STAT3) was found to play a role in conferring anoikis resistance to pancreatic cancer cells and in promoting metastasis." (PMID 25743109, 2015). "To further determine whether STAT3 activation was associated with MEK inhibition, we tested another small molecule MEK inhibitor PD98059 in a different K-Ras mutant pancreatic cancer cell line, AsPC-1 (G12D)." (PMID 25961376, 2015). "Pathway analysis of its target genes via DAVID showed enrichment (FDR < 5 %) of genes in the Jak-Stat signaling pathway, including several receptors of interleukins (PTPN6, IL22RA1, CREBBP, IL28RA, IL15RA, PIK3R5, STAT3) and pancreatic cancer pathways (VEGFC, ACVR1B, PIK3R5, EGF, STAT3)." (PMID 26572553, 2015). "Our current and previous study indicated that STAT-3 is up regulated in pancreatic cancer cells." (PMID 25869100, 2015). "Taken together, our data suggest that MMP-13 may serve as a downstream effector of the leptin -JAK2/STAT3 cascade responsible for pancreatic cancer cell invasion." (PMID 25948792, 2015). "Furthermore, silibinin treatment reduces STAT3 activation, c-MYC and GLUT1 expression, and the number of proliferating cells in pancreatic tumors, while preventing tumor-induced body-weight loss." (PMID 26510913, 2015). "To determine the causal relationship between STAT3 activation and c-MYC expression in human pancreatic cancer, we investigated the TCGA pancreatic cancer dataset for a correlation between pSTAT3 levels and c-MYC protein expression in 106 primary tumor specimens." (PMID 26510913, 2015).
pancreatic cancer (continued). "The results demonstrate that the combination treatment exhibited stronger inhibition of the colony forming ability than a single agent, and indicate the benefit and rationale to block both MEK and STAT3 oncogenic pathways in K-Ras mutant pancreatic cancer cells." (PMID 25961376, 2015). "Our results are consistent with the general consensus that obesity is a contributing factor to increased pancreatic cancer growth and offer a contributing mechanism for enhanced tumor growth mediated by leptin induced changes in STAT3 and/or PI3K-AKT signaling." (PMID 25919692, 2015). "These novel STAT3 inhibitors show significant inhibition of STAT3 activation, STAT3 reporter promoter activity, and the growth of breast and pancreatic cancer cell lines in vitro and xenograft breast tumors derived from TNBC MDA-MB-231 cells, via oral administration." (PMID 24743778, 2014). "Expression of miRNA130b, which targets STAT3, inhibits pancreatic cancer cell proliferation." (PMID 24743778, 2014). "CD147 may also serve as a promising therapeutic target for highly aggressive pancreatic cancer and a surrogate marker in STAT3-targeted molecular therapies." (PMID 25268615, 2014). "Targeting inflammatory mediators such as STAT3, ROS, and autophagy may act as an effective and viable strategy for pancreatic cancer management." (PMID 24796733, 2014). "To test the hypothesis that STAT3 is a critical downstream effector of PKCζ in pancreatic cancer cells, we assessed whether expression of a constitutively active STAT3 construct (STAT3-C) could rescue the effects of PKCζ inhibition in Panc-1 cells." (PMID 24015205, 2013). "Taken together, these data demonstrated that miR-130b could inhibit cell growth and invasion of pancreatic cancer by targeting STAT3." (PMID 24040078, 2013). "Moreover, the dual luciferase assay revealed that STAT3 was directly targeted by miR-130b, which was further confirmed by the inverse expression of miR-130b and STAT3 in pancreatic cancer samples." (PMID 24040078, 2013). "Given the striking similarity between the reported phenotype of STAT3 inhibition and the phenotype we observed with inhibition of PKCζ, we asked whether PKCζ expression regulates STAT3 activity in pancreatic cancer cell lines." (PMID 24015205, 2013). "Furthermore, inhibition of PKCζ expression significantly reduced constitutive STAT3 phosphorylation in pancreatic cancer cells grown in culture, and as orthotopic tumors." (PMID 24015205, 2013). "Treatment of pancreatic cancer cells with S3I-201, a small molecule that disrupts STAT3 SH2-phospho-tyrosine interactions, reduced STAT3 activation and significantly reduced anchorage-independent growth and cellular invasion, similar to the effect of PKCζ inhibition." (PMID 24015205, 2013). "Furthermore, STAT3 knockdown using ShRNA reduced pancreatic cancer cell invasiveness and MMP-7 expression in nude mice." (PMID 24199193, 2013). "Furthermore, inhibition of STAT3 activity in pancreatic cancer cells also reduces cell survival, invasion and tumor growth." (PMID 24015205, 2013). "Like NF-κ B, Stat3 is an attractive target for therapies treating pancreatic cancer." (PMID 24474939, 2013). "Inhibition of STAT3 sensitizes pancreatic cancer cells to tumor growth inhibition and apoptosis induced by Src or EGFR inhibitors, suggesting that co-inhibition of STAT3 may increase the efficacy of targeted therapeutics." (PMID 24015205, 2013). "Furthermore, the correlation between the expression of miR-130b and STAT3 in pancreatic cancer samples was further explored." (PMID 24040078, 2013). "Taken together, these data demonstrate that increased cellular STAT3 activity can rescue the anti-oncogenic phenotype of PKCζ RNAi cells, and demonstrate that PKCζ mediates pancreatic cancer cell transformation, at least in part, through regulation of STAT3 activity." (PMID 24015205, 2013).
pancreatic cancer (continued). "Interestingly, STAT3 is often constitutively activated in pancreatic tumors and pancreatic cancer cell lines, and activated STAT3 promotes pancreatic cancer cell survival, transformed growth, invasion, and tumor metastasis." (PMID 24015205, 2013). "The combination of Src and EGFR inhibition with Gemcitabine treatment in STAT3-mediated therapy-resistant pancreatic tumors was also effective at inhibiting the growth of xenografts of both therapy-sensitive and -resistant pancreatic cancer cells in vivo without increasing toxicity." (PMID 24499623, 2013). "Therefore, one mechanism by which PKCζ expression positively regulates the oncogenic phenotype of pancreatic cancer cells is by promoting constitutive STAT3 activity." (PMID 24015205, 2013). "Interestingly, inhibition of PKCζ significantly reduced constitutive STAT3 activation in pancreatic cancer cells in vitro and in vivo." (PMID 24015205, 2013). "Furthermore, STAT3 knockdown inhibited the cell growth and invasiveness in pancreatic cancer both in vitro and in vivo, and markedly decreased VEGF and MMP-2 expressions." (PMID 24040078, 2013). "In this study, we explored whether XZH-5 can inhibit STAT3 phosphorylation and induce apoptosis in human breast and pancreatic cancer cells that also express elevated levels of STAT3 phosphorylation." (PMID 23056374, 2012). "It is known that a large percentage of pancreatic cancers feature aberrantly activated STAT3." (PMID 22615549, 2012). "In addition to regulating the transcriptional activity of STAT3, APE1 also exerts redox control of other transcription factors, which have been implicated in pancreatic cancer (such as HIF-1α and NF-κB)." (PMID 23094050, 2012). "Our results indicate that XZH-5 may be a potential therapeutic agent for breast and pancreatic cancers with constitutive STAT3 signaling." (PMID 23056374, 2012). "Since constitutive phosphorylation of Stat3 has been detected in a variety of human cancers including pancreatic tumors and PC cell lines, we examined whether ATC or aATC can induce increased apoptosis of AT-101 sensitized tumor cells via IFN-γ/Stat pathways." (PMID 23185240, 2012). "In the present study, we investigated whether silencing of STAT3 in pancreatic cancer cells modulates tumor cell growth and invasiveness in nude mouse xenografts and determined the underlying signaling mechanisms involved using a cDNA microarray." (PMID 21991388, 2011). "In the present study, we used AG490 to deplete Stat3 protein in the human pancreatic cancer cell line SW1990 and IL-6 to activate Stat3 protein in the human pancreatic cancer cell line Capan-2; we then investigated the changes in cell proliferation and invasion." (PMID 20482858, 2010). "Therefore, there is a strong relationship between Stat3 activity and the invasive ability of human pancreatic cancer cells." (PMID 20482858, 2010). "Our aim was to demonstrate that the Stat3 signaling pathway may be critical for the invasive behavior of pancreatic tumors." (PMID 20482858, 2010). "The Stat3 signaling pathway may provide a novel therapeutic target for treatment of pancreatic cancer." (PMID 20482858, 2010). "It is presently unclear whether BITC or sulforaphane have any inhibitory effect on STAT3 activation in pancreatic cancers." (PMID 19712481, 2009). "We examined whether the inhibitory activities of bioactive compounds from cruciferous vegetables, such as Benzyl isothiocyanate (BITC) and sulforaphane, extended to STAT3 activation in PANC-1 human pancreatic cancer cells." (PMID 19712481, 2009).
pancreatic cancer (continued). "Additionally, another study indicated that stimulation of the 7-nAChR receptor increased pancreatic cancer metastasis through the activation of the Janus kinase 2 (JAK2)/STAT3 signaling pathway and the Ras/Raf/MAPK/ERK kinase (MEK)/extracellular signal-regulated kinases 1 and 2 (ERK1/2) pathways." (PMID 40940782, 2025). "Additionally, E738 could also be used for the treatment of human pancreatic cancer by inhibiting the JAK2/Src-STAT3 signaling pathway." (PMID 40841966, 2025). "Based on the role of MCPIP1 as a positive regulator inhibiting the IL6/JAK2/STAT3 axis, we propose that its expression may help identify patient subgroups with high IL6/JAK2/STAT3 axis activity (i.e., pancreatic cancer patients with strong metastatic potential)." (PMID 40874680, 2025). "Ruxolitinib reportedly inhibited STAT3 activity in pancreatic cancer cells, leading to reversing tumor-mediated immune suppression to enhance T cell activation; however, whether pyroptosis of the pancreatic cancer cells occurred was uncertain." (PMID 38336839, 2024). "Therefore, targeting STAT3 or DNMT1 might represent a potential strategy in the treatment of pancreatic cancer." (PMID 39195299, 2024). "Additionally, pancreatic cancer-educated macrophages could protect cancer cells from complement-mediated cytotoxicity by up-regulating CD59 in an IL6/STAT3-dependent manner." (PMID 39518137, 2024). "Additionally, HDAC3 upregulates PD-L1 expression through the STAT3 pathway in pancreatic cancer." (PMID 38762484, 2024). "Moreover, these cells showed a rapid decrease in the phosphorylation of Stat3 at Serine-727, a site phosphorylated by PKCε, suggesting that 5-Lox activity may regulate PKCε in pancreatic cancer cells." (PMID 38746674, 2024). "Western blot analysis of pancreatic cancer cell lines proved that the combination treatment affected the levels of BCL2, known to be associated with apoptosis and cancer metastasis, and in tissues from treated mice, a decrease in BCL2 and phospho-STAT3 (Y705) was found." (PMID 38397018, 2024). "Therefore, we considered that DCLRE1B may affect the advancement of pancreatic cancer by mediating the STAT3/PD-L1 signaling pathway." (PMID 37936074, 2023). "Thus, we speculated that CDK1 might activate STAT3 via its kinase function to influence the maintenance of cancer stemness in pancreatic cancer." (PMID 37743465, 2023). "Furthermore, hepatocytes induce release of serum amyloid A via Interleukin 6 (IL-6)-mediated Signal transducer and activator of transcription 3 (STAT3) activation to promote the establishment of a hepatic PMN which facilitates liver metastasis of pancreatic cancer in a xenograft mouse model." (PMID 37941082, 2023). "The IL-6/STAT3 signaling pathway has been proposed as a major linking mechanism between the inflammatory tumor microenvironment and pancreatic cancer, which may promote the initiation and progression of tumors by regulating oncogenes and epigenetic modifications of tumor suppressor genes." (PMID 36105933, 2022). "In addition, the special genomic, proteomic, and metabolomic features of pancreatic cancer patients should also continue to be studied in depth, with a multi-omics macro-cut into the role of STAT3 in pancreatic cancer, leading to the design of more effective STAT3 inhibitors." (PMID 36291659, 2022). "However, knockdown of ADAM17 or treatment with anti-ADAM17 antibody MEDI3622 resulted in regression of pancreatic tumors, accompanied by down-regulated EGFR/STAT3 signaling, increased cytotoxic T cells, and decreased granulocyte-like medullary inhibitory cells in mouse models of pancreatic cancer." (PMID 36466812, 2022). "Therefore, we explored whether miR-301a deletion in PSCs can reduce Stat3 activation in pancreatic cancer cells." (PMID 35211358, 2022).
pancreatic cancer (continued). "In addition, a randomized crossover trial found that tortilla and corn chips could reduce serum levels of LDL cholesterol, which has been found to promote the proliferation of pancreatic cancer cells through activating STAT3 pathway." (PMID 35958255, 2022). "In addition, STAT3 and NF-κB pathways are also active in pancreatic cancer." (PMID 35842665, 2022). "Therefore, STAT3 inhibitors may benefit pancreatic cancer patients by inhibiting tumor growth and mediating anti-tumor immunity." (PMID 36291659, 2022). "As a result of our experiments, MBZ blocked S1P-induced phosphorylation of JAK2 and STAT3 pathways in pancreatic cancer cells, suggesting that this action may have an anticancer mechanism by regulating the expression of genes involved in the apoptosis of cancer cells." (PMID 36500220, 2022). "In a parallel study, we found that HEK293T cells with constitutively active RAS (RAS-V12) showed higher HPS expression upon p-STAT3 activation, suggesting that HPS may be downregulated by STAT3 and may contribute to KRAS-mutated pancreatic cancer cell proliferation." (PMID 33801246, 2021). "Thus, N4 can suppress STAT3 activation in pancreatic cancer cells." (PMID 33420372, 2021). "More studies are needed to elucidate the signaling pathway involved in STAT3-induced HPS expression and the HPS-mediated EPA/ACC-1 lipogenic axis in KRAS-mutant pancreatic tumors, and our study hereby proposes that HPS is a promising therapeutic strategy for KRAS-mutated-driven pancreatic cancer." (PMID 33801246, 2021). "In addition, circRNA-100782 may regulate pancreatic cancer cell proliferation through interleukin 6 (IL-6) and signal transducer and activator of transcription 3 (STAT3) as a molecular sponge of microRNA-124." (PMID 34573523, 2021). "Indeed, we also found that overexpression STAT3 cannot fully restore pancreatic cancer cell proliferation from N4 treatment, further studies are needed to determine whether N4 can suppress pancreatic cancer by targeting other tumor-related targets." (PMID 33420372, 2021). "Thus, hPSCs secrete factors that stimulate STAT3 activation in pancreatic cancer cells." (PMID 34440697, 2021). "Additionally, green tea polyphenols may potentiate gemcitabine activation and promote PARP cleavage and caspase-3-related apoptosis in pancreatic cancer cells, as a consequence of STAT3 inhibition." (PMID 34948455, 2021). "Thus, we proved that Cc/Glt NM could promote apoptosis by stimulating ER stress and regulating STAT3 phosphorylation in pancreatic cancer cells." (PMID 32891174, 2020). "Thus, targeted inhibition of STAT3 could be a novel therapeutic agent applied in clinic to fight against pancreatic cancer." (PMID 32457835, 2020). "Thus, USP5 may promote pancreatic cancer progression and metastasis through enhancing STAT3 signaling." (PMID 33123271, 2020). "Interestingly, S1PR1 was also one of the target genes of STAT3 and S1PR1/STAT3 formed a positive feedback loop, which might play important roles in the progression of pancreatic cancer." (PMID 31438989, 2019). "Moreover, the STAT3/Bmi1 axis may be important downstream effectors determining the biological reactions of pancreatic cancer cells during chemotherapy." (PMID 31244991, 2019). "Moreover, low-dose VPA increased the reactive oxygen species (ROS) production, which activated AKT to further stimulate the activation of STAT3, Bmi1 expression and eventually promoted the migration and invasion of pancreatic cancer cells induced by gemcitabine." (PMID 31244991, 2019). "Thus, it would be of great interest to further investigate whether upregulation of GPR87 in pancreatic cancer is attributed to STAT3-mediated transcriptional upregulation." (PMID 28288630, 2017).